CDC25C (cell division cycle 25C)
Diseases named in the same sentence as CDC25C in open-access papers (continued):
Sharing a sentence is not in itself a finding about the gene and the disease.
esophageal squamous cell carcinoma (1 paper, 2020). Esophageal squamous cell carcinoma (ESCC) is a type of esophageal carcinoma (EC) that can affect any part of the esophagus, but is usually located in the upper or middle third. "After knocking down the expression of CDC25C in human esophageal squamous cell carcinoma cell lines, the cells were found to decrease sensitivity to radiotherapy and inhibited cell proliferation activity." (PMID 32518522, 2020). "In studies of esophageal squamous cell carcinoma, overexpression of CDC25C predicts postoperative response and prognosis in patients receiving radiotherapy." (PMID 32518522, 2020).
microcephaly (1 paper, 2023). A congenital or acquired developmental disorder in which the circumference of the head is smaller than normal for the person's age and sex. "However, whether CDC25C takes part in neurogenesis-associated diseases such as microcephaly is unknown." (PMID 36675024, 2023).
myelodysplastic syndrome (1 paper, 2016). A clonal hematopoietic disorder characterized by dysplasia and ineffective hematopoiesis in one or more of the hematopoietic cell lines. "The mechanism of CDC25C alternative splicing and its downstream effects may be pertinent to the role of SRSF2′s point mutation in the development of myelodysplastic syndrome." (PMID 27552991, 2016).
neuroblastoma (1 paper, 2011). Neuroblastoma (NB) is the most common solid, extracranial childhood tumor.
oesophageal cancer (1 paper, 2017). "Conceivably, like knockdown of LIM proteins, CDC25C overactivation in oesophageal cancer cells might abrogate the G2 checkpoint in response to IR, leading to decreased cell survival." (PMID 28094252, 2017).
ovarian tumor (1 paper, 2020). "The differences of CDC25C (P = 0.000), pCDC25CSer216 (P = 0.001), CDK1 (P = 0.000), CHK1 (P = 0.000), CHK2 (P = 0.000), PLK1 (P = 0.000) and Aurora A (P = 0.000) expression had statistical significances among these ovarian tumor groups." (PMID 32393310, 2020).
papillary thyroid carcinoma (1 paper, 2020). "In human papillary thyroid carcinoma BCPAP cells, apigenin induced G2/M cell cycle arrest and DNA damage through suppressing the expression of Cdc25c and triggering the accumulation of ROS production." (PMID 33138135, 2020).
paraganglioma (1 paper, 2025). A benign or malignant neoplasm arising from paraganglia located along the sympathetic or parasympathetic nerves. "Distinct from CDC25A and CDC25B, the methylation level of CDC25C decreased in most tumor tissues, including KIRP, LUSC, PRAD, UCEC, LIHC, BLCA, LUAD, and pheochromocytoma and paraganglioma (PCPG)." (PMID 40216745, 2025).
scrapie (1 paper, 2020). A fatal disease of the nervous system in sheep and goats, characterized by pruritus, debility, and locomotor incoordination. "In addition, the brains of scrapie-affected hamsters show evidence of cell cycle activity with an increase in the proteins polo-like kinase (PLK) 1 and cyclin B1, and a decrease in PLK3 and Cdc25C." (PMID 32108870, 2020).
cancer (109 papers, 2009 to 2026). A tumor composed of atypical neoplastic, often pleomorphic cells that invade other tissues. "For instance, CDC25C plays a critical role in regulating the G2/M phase of the cell cycle, and its expression changes are implicated in cancer growth." (PMID 40613523, 2025). "The results indicated that compound 150441 effectively inhibited the expression of Aurora A and cyclin B1 and the activation of PLK1, CDK1, and CDC25C, causing cancer cell arrest in the G2 phase." (PMID 40126184, 2025). "Dysregulation of CDC25C is associated with poor prognosis and is often linked to cancer progression." (PMID 40034437, 2025). "Overexpression, alternative splicing, and phosphorylation of CDC25C are intricately linked to tumorigenesis and the formation of polyploid giant cancer cells." (PMID 40216745, 2025). "Among them, CDC25C was the hub gene with diagnostic and prognostic value, and was associated with the survival outcomes in 10 cancers." (PMID 41019083, 2025). "Down-regulation of CDC25C can induce cell cycle arrest at the G2/M phase, and its abnormal expression is associated with cancer initiation, development, metastasis and poor prognosis." (PMID 38713252, 2024). "Extensive research has demonstrated that abnormal expression of CDC25C is associated with the progression of various types of cancer." (PMID 38511143, 2024). "The regulation of CDC25C is closely associated with tumorigenesis and is considered a possible target for cancer conduct." (PMID 35721186, 2022). "CDC25C was upregulated in carcinoma tissue and associated with the paralogous cluster miRNAs, but no seed matches were identified; it is possible that the same regulator that increases the expression of these miRNAs influences CDC25C expression." (PMID 29725503, 2018). "CDC25B, CDC25C and phospho-CDC25C (Ser216) were associated with malignant features and aggressive cancer phenotypes." (PMID 20500813, 2010). "CDC25B, CDC25C and phospho-CDC25C (Ser216) expression were associated with malignant features and aggressive cancer phenotypes." (PMID 20500813, 2010). "In addition, CDC25C was significantly associated with immune cell abundance in 13 cancers, TMB in 21 cancers, and microsatellite instability in 10 cancers." (PMID 41019083, 2025). "High CDC25C expression was associated with low survival in 9 cancers besides HCC." (PMID 41019083, 2025). "Investigating the underlying mechanisms of CDC25C in cancer initiation and progression may provide a new insight into the diagnosis and treatment of human tumors." (PMID 32518522, 2020). "Furthermore, CDC25C showed good diagnostic value and may be involved in the progression of multiple cancers, making it an important pan-cancer target for APs." (PMID 41019083, 2025). "The expression of 74 genes can influence the activity of multiple cancer hallmark-related pathways, such as MELK, CDC25C, and AURKA." (PMID 39940833, 2025). "CDC25C was associated with survival of 10 cancers, MSI in 10 cancers, TMB in 21 cancers, and immune cell abundance in 13 cancers." (PMID 41019083, 2025).
cancer (continued). "In our observations, SFN treatment of cancer cells led to the decrease of cyclin B1/CDC2 complex association and phosphorylation of CDC25C." (PMID 37189614, 2023). "Since CDC25C is the link among CDK1, CCNB, and PLK1, and the expressions of CDC25C among ten cancer cell lines are also downregulated, we added CDC25C for the experiment validation step." (PMID 37007025, 2023). "Since CDC25C is commonly overexpressed in cancer cells to facilitate G2/M transition by dephosphorylating CDK1, we assessed the phosphorylation level of CDK1 at Y15 (p-CDK1-Y15)." (PMID 38062028, 2023). "It should be noted that several studies have shown that the inactivation or degradation of CDC25C promotes the development of cancer by accelerating mitosis." (PMID 37189614, 2023). "Apart from that, the translational activation of MAPKAPK2 in cancer cells after GRO-NLs exposure suggests its putative role in the phosphorylation of Cdc25C at Ser216, which assists in the cytoplasmic degradation, inactivation, and growth inhibition of cells." (PMID 37298090, 2023). "When searching the literature for previous works testing the correlation between CDC25C expression and cancer outcomes, we came across several studies; however, nearly all of them based their analysis on CDC25C mRNA levels." (PMID 36830899, 2023). "Activation of the MAPK/ERK pathway has been reported to induce cancer cells to arrest in G2/M phase by regulating the protein expression levels of p21 and CDC25C." (PMID 35656311, 2022). "Through UALCAN database, the CDC25C expression was found significantly higher in 22 cancers when compared to that of normal tissues." (PMID 35574406, 2022). "Higher expression of CDC25C has been observed in multiple cancers, including bladder, gastric and colorectal cancers, associated with poor prognosis." (PMID 35574406, 2022). "Hyperexpression of CDC25A and CDC25B in various cancers is common, but little is known about the expression of CDC25C in tumors and its mechanism of action." (PMID 32518522, 2020). "Recently, it has evident that changes in the expression of CDC25C are closely related to tumorigenesis and tumor development and can be used as a potential target for cancer treatment." (PMID 32518522, 2020). "As the key downstream of CDC25C inhibiting apoptosis, the expression of survival protein Survivin increases in multiple malignant tumors." (PMID 32518522, 2020). "CDC25C knockdown in cancer cells or CDC25C KO in MEFs greatly abrogated the ability of FHL1 knockdown by increasing the survival of the irradiated cells." (PMID 28094252, 2017). "LicA treatment decreased the expression of MDM2, Cyclin B1, Cdc2 and Cdc25C in H460 and A549 cancer cell lines." (PMID 28805696, 2017). "FHL1 regulated G2/M arrest mainly through CDC25C because CDC25C knockdown in cancer cells or CDC25C KO in MEFs greatly abolished such effect." (PMID 28094252, 2017). "We found that IR-inducible LIM proteins, such as FHL1, inhibit CDC25C activity, resulting in radioresistance in cancer cells." (PMID 28094252, 2017). "It is gradually recognized that the regulation of CDC25C expression in response to DNA damage in cancer cells involves complex processes that are yet to be explored (e.g., alterative splicing)." (PMID 27801830, 2016). "Our data indicate that CLU silencing induces a constitutive activation of Cdc25C, which delays mitotic exit and hence sensitizes cancer cells to mitotic‐targeting agents such as taxanes." (PMID 27198502, 2016). "In this study we provide novel insights into the previously unexplored role of CLU in mitosis in cancer cells showing that CLU affects mitosis exit by regulating Cdc25C activity." (PMID 27198502, 2016). "In a cell-free experiment, it inhibited the activity of Cdc25B and C directly 42, and it was also shown to alter the expression profile of the active or inactive form of Cdc25C in different cancer cell lines 35,43,44." (PMID 26228523, 2015).
cancer (continued). "PIM1 is known to enhance cancer cell survival by phosphorylating a number of target genes such as p21waf1, p27Kip1 and Cdc25C." (PMID 25834102, 2015). "Overexpression of Gls2 in cancer cells induced phosphorylation of the protein phosphatase cdc25c, a key regulator in the G2/M checkpoint, together with a significant reduction in p21 and cyclin D1." (PMID 24330717, 2013). "In carcinoma cells the G2/M cell cycle checkpoint is dysregulated, resulting in increased activation of Cdc25C and Cdc2 leading to accelerated cell growth." (PMID 23874958, 2013). "Arrest in G2/M phase of cancer cells by other OSCs, such as DADS, DAS and DATS, has been found to be associated with down-regulation of cdc25c proteins." (PMID 22389672, 2012). "14-3-3epsilon plays a role in the G2 DNA damage checkpoint response, which results in G2 phase arrest in different cancer cell lines due to inhibition of cdc25C." (PMID 20565895, 2010). "In cytoplasm, nucleus and cytoplasm/nucleus high phospho-CDC25C (Ser216) expression was identified in 50%, 70% and 77% of the carcinomas, respectively." (PMID 20500813, 2010). "CDC25C was highly expressed in all cancers and was involved in cell cycle-related functions." (PMID 41019083, 2025). "To explore broader oncogenic relevance, we conducted a pan-cancer assessment of CDC25C." (PMID 41019083, 2025). "It has been reported that CDC25C was overexpressed in many cancers and correlated with prognosis." (PMID 38713252, 2024). "The effect of CDC25C rs3734166 polymorphic genotypes on age at cancer diagnosis implies that this SNP may affect CDC25C gene function by delaying cell cycle progression in response to stress, leading to earlier tumorigenesis in LSVH." (PMID 39457514, 2024). "Furthermore, we found that FHL1 interacts with CDC25C, which was confirmed as an important factor in cancer development." (PMID 35142956, 2023). "The pan-cancer analysis was performed to explore the role of CDC25C in other cancers." (PMID 35574406, 2022). "Of note, prolonged survival with high CDC25C expression was observed in several cancers." (PMID 35574406, 2022). "In the future, miRNA, signal inhibitors, specific antibodies, drug/peptide/small molecule based on CDC25C may be developed for the early diagnosis and clinical treatment of malignant tumors." (PMID 32518522, 2020). "More and more evidences showed that CDC25C could be used as a biomarker of the diagnosis and prognosis in a variety of malignant tumors." (PMID 32518522, 2020). "Furthermore, we found known (e.g. TP73, NTRK1, and CDC25C) and novel cancer biomarkers at the multi-cancer, cancer type and cancer subtype levels." (PMID 32152446, 2020). "It is suggested that the increased expression of CDC25C may be related to anti-apoptotic signals of cancer." (PMID 32518522, 2020). "With intensive studies on CDC25C, researchers have gradually realized that this cell cycle regulator can play an important role in clinical treatment as a potential target for a new generation of cancer therapy." (PMID 32518522, 2020). "The CDC25C protein is a phosphatase responsible for the dephosphorylation and activation of CDK1 to promote the transition of cells to mitosis, so NS1-inactivated CDC25C could inhibit cancer cell proliferation." (PMID 31487941, 2019). "The top 1 network in the spleens of A.SW mice was categorized as “Cell Cycle,” “Reproductive System Development and Function,” and “Cancer,” including down-regulated genes: cyclin family (Ccne1, Ccnb1, and Ccnb2) and cell division cycle family (Cdc20, Cdc25b, and Cdc25c)." (PMID 30941144, 2019). "Indeed, many researchers have reported the abnormal expression of Plk1 and Cdc25C in several cancer cells." (PMID 29531821, 2018). "In previous studies, overexpression of CDC25C has been reported in a limited number of carcinomas." (PMID 20500813, 2010).
cancer (continued). "CDC25C regulates G2/M progression and mediates DNA damage repair, and upregulation of CDC25C in various malignant tumors suggests that it could serve as a potential biomarker for cancer diagnosis and prognosis prediction." (PMID 37537521, 2023). "Finally, the role of CDC25C in pan-cancer was analyzed using TCGA database." (PMID 35574406, 2022). "Therefore, it is reasonable to think that CDC25C can be used as a new target for cancer resistance." (PMID 32518522, 2020). "To further determine whether there existed difference of the activation of DNA damage checkpoint responses between radioresistant cancer cells and parental cells, we examined the expression levels of activating phosphorylated Chk1, Chk2, cdc25C, and ATRIP by western blotting after IR treatment." (PMID 29567990, 2018). "Indeed, limited studies have emphasized on the evaluation of CDC25C expression in cancers." (PMID 27801830, 2016). "Additional evidence for the antiproliferative potential of phenylpropanoids comes from studies on cinnamaldehyde and its analogs, which induced G2 arrest in human cancer cells by downregulating key G2/M regulators (CDK1, CDC25C, MAD2, CDC20)." (PMID 41009502, 2025). "Decreased expression of CDC25C, CDK1, and CCNB1 inhibited the transfer of cell cycle from G2 phase to M phase, resulting in the inhibition of cancer cell proliferation." (PMID 40313621, 2025). "qRT-PCR analysis showed that the mRNA expression levels of TIMP1, CDC25C, ATP2A1, and TIGD1 were upregulated in cancer cell lines compared to normal cell lines, whereas NRG1 and DMPK exhibited reduced expression in cancer cell lines." (PMID 41190067, 2025). "Undeniably, since the study focused on the relationship between CDC25C and LUAD, only survival and expression analyses were performed in the pan-cancer." (PMID 35574406, 2022). "By analysing the TCGA database, we found that CCNB1, CDC25C, CENPM, and EXO1 were highly expressed in almost all of the 33 cancers, and we also noticed significant high expression in LUAD." (PMID 35646074, 2022). "MiR‐22 has also been found to target many genes encoding cancer‐associated proteins, including the TET2 tumor suppressor, HDAC6, ERBB3, CDC25C, EVI‐1, and P21, which play different roles in different types of cancer." (PMID 33159388, 2021). "Our investigations demonstrate that TOPK directly interacts with CHK1 and Cdc25C during cell-cycle progression, and that suppression of TOPK leaves cancer cells vulnerable to DNA damage during CHK1-mediated checkpoint activation." (PMID 33168956, 2021). "We found that the hub genes (BUB1B, CDC25C, CENPE, kinesin and CCNB1) make up an essential response across many cancer types." (PMID 31396397, 2019). "We selected several known important proteins in cancer biology, including STAT3, CDC25C, and PLK1, and validated RPPA data by western blotting." (PMID 30221473, 2018). "Consistent with the antiproliferative effect of metformin in cancer cells, our data shows a decreased expression in many cell cycle kinases such as CDKs, CDC45, and CDC25C." (PMID 29085821, 2017). "Our findings provide a novel vertebrate cell cycle link between TRIB2 and CDC25C, and suggest regulated TRIB2 functions during the cell cycle that are likely to be important in cancer." (PMID 27563873, 2016). "Most of the miR-22-regulated targets involved in carcinoma development pathway were recently validated, including MYCBP, MCM7, CDC25C, and CCNA2, all of which are responsible for the cell proliferation." (PMID 27738335, 2016).